CCL21 (C-C motif chemokine ligand 21)
Diseases named in the same sentence as CCL21 in open-access papers (continued):
Sharing a sentence is not in itself a finding about the gene and the disease.
tumor (continued). "In the viral cytokine receptor pathway, upregulated genes (p = 1.39 × 10−5), including TNFRSF1A, CCL21, IL2RB, IL22RA1, and XCR1, suggest that oncolytic viruses exploit tumor-specific immune evasion mechanisms to selectively lyse tumor cells, activating anti-tumor immunity via DAMPs and PAMPs." (PMID 40406701, 2025). "Contrastingly, CCL21 and VEGFC gene expression, as well as CCL21 and VEGFC protein drainage to lymph nodes are important biomarkers of the SA-HFIRE-induced vascular remodeling and extent of ablation within the tumor." (PMID 39998766, 2025). "Preclinical studies have shown that treatment with dendritic cells (DCs) engineered to express the chemokine CCL21 can enhance the infiltration of DCs, CD4+, and CD8+ T cells into the lung tumor microenvironment (TME), thereby effectively reducing tumor burden." (PMID 40428349, 2025). "Intratumoral administration of CCL21-modified DCs has been shown to promote CD8+T cells and Th1 cells infiltration into the tumor microenvironment of ICI-resistant NSCLC mouse models, while the combination of CCL21-DCs with αPD-1 therapy further enhances antitumor efficacy." (PMID 41268560, 2025). "In addition, the oHSV treatment resulted in higher expressions of Ccl4, Cxcl9, Ccl21 and Cxcl10 in the MC38 tumours." (PMID 39219056, 2025). "Moreover, a large quantity of CCL21, a HEV-secreted chemokine related to B and T cell recruitment into TME24, was found to be present in TLS-adjacent tumor tissues." (PMID 39827246, 2025). "Additionally, intratumoral infusion of CCL21 over-expressed DCs was shown to increase intratumoral CD8 T cell infiltration and reduce tumor burdens in a transgenic lung cancer mouse model." (PMID 39076974, 2024). "Except for genes that might have been highly expressed in the lymph nodes (CCL21, LTB) and has already previously identified related to tumor metastasis gene (MMP9), we selected GPNMB as target gene for further study." (PMID 38706915, 2024). "Several of these chemokines including CCL21 (~224-fold) and CXCL13 (~66-fold) were previously shown to exert immunosuppressive effects by recruiting CD4 and CD8 T cells and DC in the TME, thereby inhibiting tumor progression and metastasis." (PMID 39766038, 2024). "Because of this, we hypothesized that CCL21, secreted by the GBM cells, drives pDC recruitment to the tumor." (PMID 39456552, 2024). "Although the addition of CCL21 did not yield significant therapeutic benefits overall, it showed promise in one patient with remarkable tumor lymphocyte infiltration, prompting further investigation of CCL21 in combination therapies." (PMID 39114657, 2024). "There was no comparable difference in migration efficacy between CCL21 protein and tumor co-culture conditions." (PMID 39456552, 2024). "Moreover, these CCL21-induced pDCs show a regulatory function, directly suppressing CD8+ T cell proliferation and contributing to the immunosuppressive tumor microenvironment." (PMID 39456552, 2024). "On the one hand, CCL21 interacts with CCR7 to control the transfer of immune cells such as DCs and T cells to lymphatic vessels and lymph nodes, which in turn enhances the anti-tumor immune response." (PMID 37307828, 2024). "Furthermore, the highly expressed DEGs of fibroblasts in LNM included immune-related genes (CCL21, CCL19, CCL2, and MYC), metabolism-related genes (STEAP4, FABP4, DPT, and APOE), and genes related to tumor proliferation and progression (RGS, CCN, and MYC)." (PMID 37221625, 2023). "Finally, CCL21 ELISAs performed on conditioned medium (CM) from CT-2A and GL261 GBM tumor cells or primary microglial cells confirmed higher CCL21 secretion from tumor cells when compared to microglia." (PMID 37314567, 2023). "After anti-HER2 treatment, in tumours exhibiting HER2 amplification, there would be a downregulation in the release of cytokines, including CCL2, CCL21, VEGF, and CXCL1, which leads to an amelioration of the immunosuppressive factors within the tumour microenvironment." (PMID 37720943, 2023).
tumor (continued). "CCL21 and ICAM-1 were overexpressed in CD31-positive endothelial cells in tumor tissues and endothelial venules of tumor-draining lymph nodes, and an increase in naive CD8+T cells can be found in tumor tissues and draining lymph nodes." (PMID 36761748, 2023). "Our results highlight the previously unappreciated importance of nonclassical monocytes in shaping the tumor microenvironment via CCL21 production and CD8+ T cell recruitment." (PMID 37426658, 2023). "It was recently demonstrated that culturing of activated murine CD8+ T-cells on a “Synthetic Immune Niche” (SIN), consisting of immobilized CCL21 and ICAM-1, enhances T-cell expansion, increases their cytotoxicity against cultured cancer cells and suppresses tumor growth in vivo." (PMID 36937426, 2023). "However, the function of the CCL19, CCL21/CCR7 and CXCL13/CXCR5 axes in tumor immunity is complicated." (PMID 37215990, 2023). "In addition, lymphatic vessels express large amounts of CCL21, which provides migration guidance for tumor cells expressing the CCL21 receptor CCR7 and drives tumor cells to migrate into the lymphatic system." (PMID 36831512, 2023). "However, if located on cancer cells, CCR7 and its ligands (CCL19/CCL21) is a vital axis for carcinogenic properties, such as epithelial-mesenchymal transition (EMT) tumor invasion and migration." (PMID 35938006, 2022). "The sub‐clustering of ECs revealed six subtypes, including extra‐alveolar capillary EC (cEC) (FCN3+EDN1+PLVAP+), alveolar cEC (HPGD+EDNRB+IL1RL1+), arterial EC(GJA5+FBLN5+DKK2), lymphatic EC (CCL21+TFF3+FABP4), INSR+ tumour EC (INSRhiHSPG2+PLVAP+), and ACKR1+ tumour EC (ACKR1+SELP+IL1R1+)." (PMID 35184398, 2022). "Activation of CCL21/CCR7 promoted proliferation and migration of tumour cells." (PMID 35280672, 2022). "CCL3, CCL19, CCL21, and XCL1 exhibited potent anti-tumor activities in vivo, although they might differentially regulate immune cells in the TME and antigen transfer to lymph nodes." (PMID 36654820, 2022). "PNAd+ CCL21+ vessels developed spontaneously, and supported the infiltration of naive CD8 T cells that differentiated into functional effectors after intratumoral activation and significantly delayed tumor outgrowth." (PMID 36189308, 2022). "Interestingly, tumor-intrinsic PKD3 has been described to promote immune escape by enhancing expression of Fas and PD-L1 as well as secretion of TGF-β, CCL-21 and IL-10, all of which are critical to establish an immunosuppressive tumor microenvironment." (PMID 35440091, 2022). "This recruitment, made possible by upregulation of CCL21, then leads to the activation of T cells in the primary tumor rather than the lymph node, leading to a strong immune response against primary tumor cells." (PMID 36158182, 2022). "Immune cells can also directly influence the phenotype and function of tumor vessels through various cytokines, such as cytokines that inhibit tumor angiogenesis (interferon-α, interleukin-12, interleukin-18 or tumor necrosis factor) and chemokines (CXCL9, CXCL10 or CCL21)." (PMID 36569915, 2022). "CC chemokine ligand 21 (CCL21) is a chemokine without inflammatory responses, which attracts normal immune cells and metastasizing tumor cells to lymph nodes by activating the CCR7 receptor." (PMID 36037155, 2022). "The CCL21/CCR7 axis has a dual role, since it can both regulate the homing of immune cells to the lymph node to prime and activate T cells, B cells, and dendritic cells and be involved in a metastatic tumor phenotype by promoting cancer cells migration." (PMID 34445452, 2021). "Analysis of HEV-lining CCL21 by scoring revealed that almost all IM-HEVs lacked detectable perivascular CCL21 (87 ± 25%), and were surrounded by densely packed tumor cells." (PMID 33430113, 2021).
tumor (continued). "As already stated in Learning From TLS Study in Non-Tumor Inflammatory Diseases to Better Understand TLS Role in Cancer, CCL21 could be therefore an interesting and translatable target for TLS induction and anti-tumor immunotherapy." (PMID 34276690, 2021). "Also, since CCL21–CCR7 axis mediates tumor metastasis, blocking CCR7 in cancer cell or inhibition CCL21 secretion can test for restrict metastasis." (PMID 34671596, 2021). "CCL21, through binding to its receptor, chemokine (C-C motif) receptor 7 (CCR7), can attract dendritic cells (DCs), lymphocytes, natural killer (NK), and natural killer T (NKT) anti-tumor effectors to the tumor site." (PMID 29687228, 2020). "BCP also suppressed the number of lipid vacuoles and F4/80+ macrophage (MΦ) and macrophage mannose receptor (MMR)+ M2-MΦs in tumor tissues and adipose tissues surrounding the lymph nodes and reduced the CCL19 and CCL21 levels in the lymph node and CCR7 expression in the tumor." (PMID 32998300, 2020). "Nevertheless, if the tumor microenvironment has favorable conditions for tumor development, then CCL19 and CCL21 may participate in Treg recruitment to the tumor niche." (PMID 33076281, 2020). "Besides, in combination with tumor-infiltrating CD8+ T cells, CCL21-expressing DCs can mediate tumor eradication." (PMID 33146700, 2020). "Initial reports suggested that CCL21 and CCL19 were anti-tumorigenic, as they could attract lymphocytes that would attack the tumor." (PMID 32340161, 2020). "In addition, adipocytes increase C–C motif chemokine ligand 19 (CCL19) and CCL21 expression in LECs and C–C chemokine receptor type 7 (CCR7) expression in tumor cells, which attracts more tumor cells to the lymphatic vessels." (PMID 33203856, 2020). "Chemokines and their receptors play an important role in directing cognate T-APC interactions in lymph nodes and spleen (e.g., CCR7 and CCL21/19), or in bone marrow (e.g., CXCR4 and CXCL12 (SDF-1α/β), or attracting Treg cells towards tumor tissue (e.g., CCR2 and CCL2 (MCP-1))." (PMID 32155856, 2020). "PD-1 blockade or CCL21-DC tumor lysate vaccine monotherapy reduced tumor burden without tumor eradication." (PMID 32570793, 2020). "After correcting for gender, race and tumor purity, we identified that B cells, CD8+ T cell, CD4+ T cell, neutrophils, dendritic cells, CCL21, age (P=0), tumor stage (P=0), macrophage infiltration (P=0.035) and CCL8 (P=0.033) were associated with clinical outcomes of BC." (PMID 33146700, 2020). "Finally, a number of gene expression profiles, comprised of genes for key chemokines such as CCL19, CCL21 and CXCL13, or a combined TH1 and B cell signature, have been utilized to determine the presence of TLS in tumor tissues." (PMID 33013886, 2020). "Our data demonstrate that s.c. administration of CCL21-DC tumor lysate vaccine results in tumor growth inhibition, but the vaccine therapy alone is not optimal." (PMID 32570793, 2020). "We observed a negative correlation between CCL21 expression and BC tumor purity (Cor = −492, P=9.83e-62)." (PMID 33146700, 2020). "Additionally, CCL21 can be upregulated by VEGF-C/VEGFR-3 signaling, which has been shown to be highly expressed in primary tumors and tumor-derived lymphatic neovasculature." (PMID 32002106, 2020). "Because the same chemokines that recruit anti-tumor leukocytes can also recruit pro-tumor leukocytes (for example CCL19 and CCL21 recruit both Tregs, mDCs, and activated T cells), therapeutically targeting chemokines or chemokine receptors in cancer is complicated." (PMID 30873179, 2019). "Importantly, anti-CD19-CAR and CCR7 conferred to NK cells an up to 5 fold increase in killing of CD19+ tumor cells and a 6 fold increase of migratory capability in response to CCL19 or CCL21, respectively." (PMID 31114587, 2019). "Expression of CCL21 was not different between tumor and non-tumor tissues (6.56±4.27 vs. 4.65±2.75, P=0.140)." (PMID 31523177, 2019).
tumor (continued). "In the 4T1.2 triple-negative breast cancer (TNBC) mouse model, ILC3s are recruited to the primary tumors by CCL21 and stimulate tumor stromal cells to release CXCL13, leading to enhanced tumor cell motility, lymphangiogenesis, and lymph node invasion by tumor cells." (PMID 32117199, 2019). "Nevertheless, a direct link between ILC3s recruitment and CCL21 enhanced tumor growth and immune tolerance was not established." (PMID 31024531, 2019). "In vivo studies show the knockdown of CCL21 in secondary lymphoid organs leads to the decrease of metastatic tumor formation, since this reduces both the chemotactic and antiapoptotic effects of CCR7-expressing tumor cells." (PMID 31555130, 2019). "Consequently, T-cells cultured on CCL21 + ICAM1-coated substrates exhibited an improved killing of cultured cancer cells, and markedly elevated tumor suppressive activity, in vivo." (PMID 29942308, 2018). "Furthermore, the expression of LT#βR-related chemokines, such as CCL21, CCL19 or CXCL13 increased in the EL4-Axl-tumor bearing mice compared to the mock control." (PMID 28423548, 2017). "Since CCL21 was found to interact with PDPN the regulation of both molecules may control the entry of CCR7+NK cells and their cytotoxicity in the tumor." (PMID 28416768, 2017). "PDPN was induced by hypoxia and its overexpression undergoes a reduction of adhesion, making it an anti-adhesion molecule in the absence of CCL21, in the tumor." (PMID 28416768, 2017). "The chemokine CCL21 is induced by TGFβ in lymphatic endothelial cells and acts on invading breast cancer cells that undergo EMT, thus permitting a functional crosstalk between the tumor cell and the lymphatic system." (PMID 27367735, 2016). "CCL21 overexpression in LTi-depleted mice did not enhance tumor growth, suggesting that LTi cells play a role in CCL21-dependent immunological tolerance." (PMID 28536374, 2016). "CCL21 expression by LECs and FRCs is modulated by VEGF-C and lymph flow in tumor microenvironment." (PMID 28036019, 2016). "For example, CCL21 and other lymphocyte specific chemokines such as EBI-1-ligand chemokine (ELC) and stromal cell-derived factor (SDF)-1alpha, showed anti-tumor immunity both systemically and locally in fibrosarcoma and ovarian tumor via activation of type 1 T cell response and IFN-γ generation." (PMID 24810425, 2014). "Categorizing tumors by the expression of either tumor-derived CXCL13, CCL19, CCL21, LTαβ or their key master regulators, such as the IRFs, may allow us to stratify patients more easily into IR+ or IR− subtypes." (PMID 24762633, 2014). "Xenograft mouse models using MCF-7 cells expressing or not expressing CCL21 show that in the presence of CCL21, tumor growth is inhibited and T cell activation is enhanced." (PMID 24762633, 2014). "In a similar manner, induced expression or ectopic delivery of LTβR downstream mediators, CCL19 or CCL21, in the TME results in inhibition of tumor growth or complete rejection of established tumors associated with increased infiltration by CD3+CCR7+ T cells and/or DCs in a range of cancer models." (PMID 24348473, 2013). "In a Matrigel assay that examined the anti-angiogenic effects of different treatments in the absence of tumor cells, the survivin-CCL21 vaccine-treated group reduced blood vessel density by approximately 3-fold more than the control groups." (PMID 21385454, 2011). "Further, there was a significant correlation between CCR7 expression and lymph node metastasis (p < 0.001); CCL21 was especially highly expressed in lymph nodes metastasis tumor cells (68%), which was not the case in primary tumor cells (P = 0.004)." (PMID 20181250, 2010). "With respect to CCL21: Lymph nodes from wildtype mice that were not challenged with tumor were characterized by minimal CCL21 immunoreactivity distributed in the matrix surrounding LYVE-1-positive lymphatic vessels." (PMID 21172016, 2010).
tumor (continued). "This therapeutic strategy is hypothesized to restore tumor antigen presentation and anti-tumor effector responses, by recruiting APC, T cells, and NK cells due to the chemotactic effect of CCL21 at the tumor site." (PMID 18644162, 2008). "In murine studies, CCL21-DC induced tumor regression, stimulated production of IFN-γ and the CXC chemokines MIG (CXCL9) and IP-10 (CXCL10) at the tumor site, and decreased local concentrations of immunosuppressive inflammatory mediators including IL-10, PGE2, and TGF-β." (PMID 18644162, 2008). "In a recent study, utilising the CCR7 ligand CCL21, we have shown that cytolytic T-cell responses were enhanced to autologous CC-10 tumours but not to syngeneic control MLE-12 tumours that also express the SV40 T antigen." (PMID 16598185, 2006). "Similarly, after co-incubation with PLIGHT- or PαCD3&LIGHT-transfected tumor cells, the mRNA levels of chemokines and vascular adhesion molecules in vascular endothelial cells, such as CXCL-2, CXCL-8, CXCL-12, CCL-21, MADCAM-1, and VCAM-1, rose by about 2- to 5-fold." (PMID 41406950, 2025). "CCR7, expressed in various lymphoid tissues, activates B and T lymphocytes and facilitates tumor cell migration by mediating interactions between tumor cells and chemokines CCL19/CCL21, and may enhance tumor cell anti-apoptotic capacity through regulation of necroptosis-related gene expression." (PMID 40547036, 2025). "CCL21 and CCL19 expressed in several stromal cells may exhibit antitumor activities at primary tumor sites because these chemokines induce the recruitment of CCR7-expressing activated dendritic cells to the tumor site." (PMID 40028039, 2025). "We did not assess CCL21 levels in blood, but patients in the upper quartile for CCL21 gene expression in tumor had longer OS (HR = 0.43, 95% CI 0.23–0.79, p = 0.005), suggesting that this biomarker may be prognostic." (PMID 40239619, 2025). "As lower expression of Lyve1 in tumor sites was identified by spatial transcriptomics analysis in this study and lymphatic angiogenesis was often driven by VEGF-families, we subsequently explored the correlation of VEGF-families with CCL21, CCL19, Pecam1 (CD31) and Lyve1 by the TCGA database of HCC." (PMID 40685403, 2025). "In the absence of nonclassical monocytes, we observed a 2.3-fold reduction in the CCL21-positive area (mm2) within the lungs, suggesting that nonclassical monocytes are necessary for CCL21-mediated early recruitment of T cells to the tissue for an effective anti-tumor response." (PMID 37426658, 2023). "When CCL21 was inhibited in mouse studies, significant reductions in nociceptive hypersensitivity and nerve fiber hypertrophy were observed along with improved behavioral events, although tumor infiltration was not affected." (PMID 35203305, 2022). "Notably, CCL19 overexpression induced higher ratios of tumor-infiltrating conventional CD4+ T and NK cells but fewer Treg cells compared to CCL21, which may partially contribute to the more prominent anti-tumor effect of CCL19." (PMID 36654820, 2022). "It has been reported to abnormally express in diverse tumor types and has been blamed for enhancing tumor migration, epithelial mesenchymal transition (EMT) and cancer stemness through combination with its two CC motif ligands: CC chemokine ligand 19 (CCL19) and CC chemokine ligand 21 (CCL21)." (PMID 35904690, 2022). "Moreover, CCL21 was not differentially expressed in four BCBMs compared to the primary tumor of the breast." (PMID 34638378, 2021). "Moreover, CCL19/CCL21 were found in tumor infiltrates of cHL, whereas the tumor nodules in NLPHD almost completely lacked these chemokines." (PMID 34778050, 2021). "The variation seen between different IDC patients with more or less severe HEV remodeling and with different degree of stromal functional disruption, with and without accumulation of CCL21 on lymphocytes, is likely to influence their ability to induce effective anti-tumor responses." (PMID 33430113, 2021).